XIAP (X-linked inhibitor of apoptosis)
Diseases named in the same sentence as XIAP in open-access papers (continued):
Sharing a sentence is not in itself a finding about the gene and the disease.
tumor (continued). "On the contrary, PCNA, cIAP-1, and XIAP were decreased in tumor tissue lysates from IL-32α Tg mice compared to non-Tg mice." (PMID 25909160, 2015). "Smac levels did not increase in response to therapy in either normal or tumour tissue, which once again contributes to a disruption of XIAP/Smac expression in cells." (PMID 26071313, 2015). "The (cyt-c + dATP)-untreated cytosol samples from these tumours showed negative linear correlation between the level of XIAP protein and the low endogenous CS-3-like activity (r=−0.480, p=0.009)." (PMID 24626292, 2014). "We found that c-IAP1 (Birc2), XIAP (Birc4), Survivin (Birc5) and Livin (Birc7) were overexpressed in ESCC tissues, while NAIP (Birc1) and c-IAP2 (Birc3) were comparable between tumor tissues and adjacent non-tumor tissues." (PMID 25216531, 2014). "We showed that the antagonist HM90822B efficiently downregulates XIAP and survivin in human EGFR-overexpressing NSCLC cells and demonstrated that this downregulation contributes to enhance cell cycle arrest and apoptosis, even to regress tumor growth in vivo." (PMID 25321484, 2014). "To test whether XIAP is involved in the inhibition of endogenous and apoptosome-generated caspase activity in cytosol from NSCLC tumours we used the heptapeptides AVPIAQK (P1) and ATPFQEG (P2) to neutralize the XIAP inhibitory action against the caspases." (PMID 24626292, 2014). "Our result also consisted with Hinnis' study that AI was not correlated with patient age, tumor size, lymph node status, histologic grading and expression of XIAP, Smac, ER and PR protein." (PMID 21645409, 2011). "A set of data, consisting with other report, showed that expression status of XIAP/Smac was not correlated with patient age, tumor size, lymph node status, histologic grading, expression of ER and PR." (PMID 21645409, 2011). "Furthermore, the apoptosis, stem cell and tumor phenotypes of Sept4/ARTS-null mice were suppressed by inactivation of XIAP, demonstrating that ARTS acts mainly by targeting XIAP in vivo." (PMID 21949740, 2011). "Remaining data revealed that the expression status of XIAP/Smac was not correlated with patient age, tumor size, lymph node status, histologic grading, expression of ER and PR." (PMID 21645409, 2011). "Our data show that long-term expression of XIAP at concentrations comparable to that in tumour cells (two- to five-fold increase) resulted in little or no resistance towards chemotherapeutic drugs." (PMID 20485285, 2010). "XIAP knockdown only sensitized tumor cells to TRAIL and not the mitochondrial pathway inducing agents." (PMID 20067634, 2010). "In support of this notion, multiple reports have shown that stable shRNA or antisense knockdown of XIAP resulted in decreased tumor cell growth, as subcutaneous xenografts in vivo, but not as culture mono-layers, in vitro." (PMID 20067634, 2010). "Furthermore, MA decreased the expression levels of NF-κB-regulated genes, including genes involved in tumor cell proliferation (Cyclin D1, COX-2 and c-Myc), apoptosis (Survivin, Bcl-2, Bcl-xl, XIAP, IAP-1), invasion (MMP-9 and ICAM-1), and angiogenesis (VEGF)." (PMID 20367887, 2010). "Here we report that transient, siRNA-mediated depletion of XIAP alone does not significantly decrease human tumor cell viability." (PMID 20067634, 2010). "We interpret the results to mean that XIAP does not have an essential role in growth and survival of tumor cell lines under normal, optimized growth conditions in vitro." (PMID 20067634, 2010). "XIAP/XAF1 ratio was significantly higher in tumor than in non-neoplastic parenchyma (FC = 3.02, p < 0.001)." (PMID 19397802, 2009).
tumor (continued). "By inhibiting XIAP, it is possible to kill tumour cells without additional impact in urothelial cancer (UC)." (PMID 18283311, 2008). "Intracellular levels of pro- and antiapoptotic factors such as cFLIP, XIAP, BCL-2 family members, and DISC formation and caspase 8 activity have been reported to regulate cell sensitivity to TRAIL-induced programmed cell death in both tumour and normal cells." (PMID 15846298, 2005). "mRNA expression of XIAP was found in all RCCs (n=59), irrespective of their tumour stages, grades or histological types." (PMID 15328523, 2004). "Since overexpression of Smac/DIABLO was able to sensitise tumour cells against anticancer drug- and TRAIL-induced apoptosis, Smac/DIABLO is thought to be a major antagonist of XIAP." (PMID 15328523, 2004). "Since XIAP expression is known to be regulated transcriptionally and post-transcriptionally, we also performed Western blot analysis in 12 arbitrarily selected RCC tumour samples of early and advanced tumour stages (pT1: n=6, pT3: n=6)." (PMID 15328523, 2004). "Consequently, the mRNA expression ratio between antiapoptotic XIAP and proapoptotic Smac/DIABLO markedly increased during progression from early (pT1) to advanced (pT3) tumour stages." (PMID 15328523, 2004). "Although investigations concerning the expression of Omi/HtrA2 in relation to tumour stage and grade are lacking, it is reasonable to assume that the disturbed balance between XIAP and Smac/DIABLO during progression of RCCs cannot be adjusted by Omi/HtrA2." (PMID 15328523, 2004). "Since tumour stage and grade are considered as major prognostic parameters in RCC, our results might also suggest that RCCs with a strong XIAP expression exhibit a poorer clinical outcome." (PMID 15328523, 2004). "Furthermore, Western blot analysis of excised HeLa tumor tissues demonstrated the overexpression of MCPIP1 in tumors treated with SLpMCPIP1 (+), and SLpMCPIP1 (+) further reduced XIAP but increased the expression of cleaved caspase-3 and cleaved PARP1 proteins compared with SLpEmpty (+) treatment." (PMID 39408613, 2024). "Notably, XIAP did not exhibit high expression in any normal tissues, suggesting a low possibility of off-tumor toxicity." (PMID 37845222, 2023). "The strength of XIAP inhibition appears crucial for its anti‐tumor effect, but was not documented in the phase II trial, which may eventually explain lack of effectivity." (PMID 36416169, 2023). "We previously reported that JL5 decreases the expression of Id1 but not XIAP in tumor xenografts." (PMID 34563224, 2021). "The anti-apoptotic proteins Mcl1 and XIAP are known targets of CDK9, and suggests that CDK9 inhibition brings about its effects by suppressing anti-apoptotic or pro-survival signaling, while simultaneously activating pro-apoptotic and tumor-suppressive pathways." (PMID 34359807, 2021). "However, this kind of homeostasis could be disturbed by a XIAP antagonist such as SMAC, which means that XIAP dysregulation in tumor must be accompanied by the disturbance of its modulators." (PMID 33138314, 2020). "Following the discovery of a potent antagonist of XIAP, small molecule mimetics of smac/DIABLO (smac-mimetics; SMs) were developed to overcome the survival benefits of IAP upregulation in cancer cells, through their antagonism of IAP activity and promotion of tumour cell death." (PMID 31947615, 2020). "IBC cells with XIAP overexpression and resultant increases in NFκB target genes regulating antioxidant and immune factors were insensitive to cetuximab-mediated ADCC and resistant to cetuximab-mediated inhibition of in vivo tumor growth when compared to the ADCC-sensitive cell lines." (PMID 30400822, 2018).
tumor (continued). "In addition to XIAP, EGFR is also a well-known tumor therapeutic target." (PMID 28057023, 2017). "Moreover, negative tumor expression of XIAP, procaspase-3 or cleaved caspase-3 predicted early biochemical progression after radical prostatectomy, both alone and after adjusting for the effects of Gleason score and pathological T stage." (PMID 26507126, 2015). "Thus, when XIAP is stably overexpressed in cell lines at levels comparable to those of tumor cells, it does not protect from apoptosis induced by commonly used chemotherapeutic agents." (PMID 26507126, 2015). "The data for the individual IAPs demonstrated that only the expression levels of cIAP1-N and Survivin-N were correlated with tumor stage and grade, while the expression levels of cIAP1-C, cIAP2, XIAP, Survivin-C and Livin were not correlated with tumor stage or grade (data not shown)." (PMID 23599779, 2013). "The correlation analysis revealed that AI was positively correlated with HER2 protein expression (rs = 0.265, P = 0.017), but not correlated with patient age, tumor size, lymph node status, histologic grading and expression of XIAP, Smac, ER and PR (Data wasn't shown)." (PMID 21645409, 2011). "SMAC mimetics have been developed with the aim to obtain drugs that allow sensitization of tumor cells for apoptosis induction by other drugs or endogenous factors by releasing apoptotic caspases from the inhibitory interaction with IAP proteins, particular XIAP." (PMID 21738708, 2011). "The lack of effect in the majority of the cell lines, and the modest and transient nature of the decreased viability in the other cell lines, suggests that in many tumor cell lines under normal in vitro growth conditions, XIAP has no essential role regulating proliferation or survival." (PMID 20067634, 2010). "Taken together, PEITC can diminish the ectopic xenograft tumor growth of GBM 8401 cells in tumor weights and volumes, which may be through the induction of apoptosis by the decrease of anti-apoptotic proteins MCL-1 and XIAP, and the increase of pro-apoptotic proteins caspase-3 and Bax." (PMID 30201893, 2018). "Thus, upregulating XIAP could confer a selective advantage to tumor cells independent of caspase inhibition." (PMID 24281211, 2010). "Among pro-apoptotic BCL-2 family genes, BID expression was lower in tumor cells, and in the IAP family, XIAP expression tended to be higher in tumors relative to non-tumor cells." (PMID 39122703, 2024). "Even though XIAP was not among the DEG list, the Ingenuity Pathway Analysis of DEGs indicated a significant enrichment of “cell death of tumor cell lines” significantly enriched in ISO-treated T24 cells (z-score = +2.203, p-value = 4.62 × 10−32)." (PMID 38339062, 2024). "Western blotting results of the tumor tissues indicated that PES significantly down-regulates the expression of EBNA1, XIAP, and c-IAP1, whereas Hsp70 expression is not reduced." (PMID 29959331, 2018). "Investigations, however, analysing the expression of XIAP and Smac/DIABLO in relation to tumour stage, grade and type are lacking up to now." (PMID 15328523, 2004). "Interestingly, several tumor cell emboli in the blood vessel and lung metastases were observed in MCF-7-XIAP 3′UTR xenografts but not in the control xenografts, indicative that XIAP 3′UTR expression promoted tumor cell metastasis from the primary lesion." (PMID 28186968, 2017).
tumor (continued). "Importantly, XIAP and cIAP2 were markedly induced in bone-marrow and lymph-node microenvironments, providing a basis for IAP antagonists as anti-tumor agents in CLL." (PMID 27223062, 2016). "If viable tumor cells such as BxPC3 and SW620 do in fact have activated caspases, our data suggests that these "death enzymes" are unlikely to be directly inhibited by XIAP, but rather by some other mechanism." (PMID 20067634, 2010). "Furthermore, the data indicated a negative correlation between XIAP and YTHDC1 in tumor samples." (PMID 40133252, 2025). "Additionally, Taqman analysis of the same tumor cDNAs for up-regulation of members of the IAP class of anti-apoptotic proteins (CIAP1, CIAP2, Survivin, XIAP, and BRUCE) similarly failed to reveal any significant transcriptional up-regulation of these genes in the Bcl-x-KO tumors (data not shown)." (PMID 19209227, 2009). "However, the nuclear translocation of XIAP is not recognized in certain tumor cells undergoing XAF1-driven apoptosis and that XAF1 has comparable proapoptotic activity in XIAP−/− and XIAP+/+ cells, indicating that XAF1 can promote apoptosis through the XIAP-independent mechanisms." (PMID 30042418, 2018).
infection (53 papers, 2009 to 2026). The state of being infected such as from the introduction of a foreign agent such as serum, vaccine, antigenic substance or organism. "Immunoblot analysis highlighted that there was a selection against XIAP deficiency by day 14 after infection, suggesting that XIAP plays important roles in guiding the outgrowth of newly EBV-infected B cells." (PMID 40674368, 2025). "Ehrlichia-induced Notch activation has recently been linked to stabilization of the X-linked inhibitor of apoptosis (XIAP), which prevents intrinsic apoptosis during infection." (PMID 36960039, 2023). "Due to the pleiotropic functions of XIAP in inducing pro-inflammatory signaling and preventing cell death in innate immune cells, XIAP-deficient mice succumb to infection." (PMID 37347786, 2023). "Epstein-Barr virus (EBV) infection was significantly more common in SAP-deficient 10/13 (76.9%) than XIAP-deficient 2/7 (28.6%) patients, as was hypogammaglobulinemia (10/13 (76.9%) vs. 1/7 (14.3%))." (PMID 31754776, 2020). "Thus, it is thought that upon infection, expansion of virus-specific T-cells is suboptimal in XIAP deficient patients." (PMID 34222142, 2021). "Since XIAP is a potent endogenous inhibitor of cell death and ST induces potent cell death of infected cells we tested whether XIAP has any impact on host susceptibility during infection with ST." (PMID 37347786, 2023). "Furthermore, infection models in XIAP-deficient mice are inconclusive." (PMID 26953272, 2017). "In summary, we identified a key role for XIAP in blockade of EBV-induced apoptosis signaling within the first week of infection." (PMID 40674368, 2025). "Further, X-linked inhibitor of apoptosis protein (XIAP) is sequestered and stabilized during infection due to increased cytoplasmic NICD." (PMID 40028182, 2025). "XIAP therefore plays a critical role in support of EBV-infected B cell transformation within the first week of infection." (PMID 40674368, 2025). "Since XIAP is the bona fide endogenous inhibitor of apoptosis we evaluated its role during infection with an acute and a chronic intracellular bacterium." (PMID 37347786, 2023). "Cytoplasmic and nuclear colocalization of NICD and XIAP was observed during infection and a direct interaction was confirmed by co-immunoprecipitation." (PMID 37594275, 2023). "In humans, patients with X‐linked lymphoproliferative disease type II (XLP‐2) lack functional XIAP but show normal blood cell counts under conditions of health and even lymphoproliferation upon infection." (PMID 36416169, 2023). "We report that during infection of macrophages and dendritic cells with various intracellular bacteria, XIAP restricts cell death and secretion of IL-1β but promotes increased activation of NFκB and JNK which results in elevated secretion of IL-6 and IL-10." (PMID 37347786, 2023). "Procaspase levels increased temporally during infection, consistent with increased XIAP levels; however, knockdown (KD) of XIAP during infection significantly increased apoptosis and Caspase-3, -7, and -9 levels." (PMID 37594275, 2023). "In comparison, increases in XIAP protein levels were demonstrated over the course of infection, with significant increases detected at 24, 48, and 72 h post-infection (hpi)." (PMID 37594275, 2023). "We performed phenotypic characterization of WT versus Xiap−/− OT1 in the same host at day 7 post-infection and observed that the XIAP promoted CD8 T cell differentiation into the memory precursors (MPEC) and central memory (T-cm) phenotype." (PMID 37347786, 2023). "We also measured the impact of XIAP on CD8 T cell response during infection with OVA-expressing Listeria monocytogenes (LM-OVA)." (PMID 37347786, 2023). "Caspase activation is inhibited in LVS infection by the concerted actions of XIAP, cIAPs and calpastatin." (PMID 35693822, 2022).